MMP2 (matrix metallopeptidase 2)
Diseases named in the same sentence as MMP2 in open-access papers (continued):
Sharing a sentence is not in itself a finding about the gene and the disease.
pulmonary fibrosis (continued). "We also found an expected increase in MMP-2 activity in the lungs of U-IPFexo treated mice, as MMP-2 increases migration and invasiveness of lung myofibroblasts during Bleo-induced pulmonary fibrosis." (PMID 36454035, 2022). "CAT significantly reduced the MMP2 and MMP9 levels in fibrotic lungs and inhibited the progression of pulmonary fibrosis." (PMID 35685407, 2022). "A recent study showed that lncRNAPCAT29 inhibits pulmonary fibrosis via downregulating RASAL1/ERK1/2 signal pathway, which suppresses the expression levels of MMP2 and MMP9 in alveolar epithelial cells and pulmonary fibroblast cell differentiation." (PMID 33791201, 2021). "MMP-2 and MMP-9 are also related to the migration of fibrocytes in idiopathic pulmonary fibrosis, as well as to myofibroblast activation in vascular fibrosis." (PMID 32429399, 2020). "Aside from serine proteases, neutrophils are an important source of matrix metallopeptidases (MMPs), such as MMP-2, MMP-8, and MMP-9, which are involved in pulmonary fibrosis." (PMID 32630825, 2020). "We also examined the levels of several other classical cytokines (including IFN-γ, IL-4, IL-12, IL-13) and several matrixmetalloproteinases (such as MMP2, MMP9) in this model of lung fibrosis." (PMID 26627341, 2015). "MMP-2 is preferentially secreted by fibroblasts and epithelial cells and has been suggested to contribute to ECM deposition in patients with pulmonary fibrosis." (PMID 26819949, 2015). "Furthermore, ELISA was used to detect pulmonary fibrosis markers COL-1, COL-3, WNT, Vimentin, β-Catenin, Fibronectin, α-SMA, N-Cadherin, E-Cadherin, TWIST, CTGF, FGF2, PDGF-α, MMP2, MMP8, MMP9, MMP13, TIMP1, TGF-β, Smad2, and Smad3 expression levels." (PMID 37812357, 2023). "As described in previously study, MMP2 and MMP9 secreted by macrophages and neutrophils in bleomycin-induced pulmonary fibrosis in early phase may play an important role in degrading the basement membrane, thereby facilitating the inflammatory cell migration." (PMID 28977826, 2017). "In the ACE2-uMSC group, the MMP-2/TIMP-2 ratio was relatively balanced, which may have promoted the protection of injury-induced pulmonary fibrosis." (PMID 25435005, 2015). "Indeed, levels of MMP-2 and MMP-9 protein and MMP7 mRNA are elevated in the lungs of patients with human idiopathic pulmonary fibrosis (IPF) and MMP-13 expression is increased in the lungs of patients with chronic obstructive pulmonary disease (COPD)." (PMID 23593124, 2013). "Gelatinase A (MMP-2) and gelatinase B (MMP-9) are two MMPs that appear to be involved in pulmonary fibrosis, but their specific roles in the process remain unclear." (PMID 15663794, 2005). "Preclinical studies of KITCL27 in bleomycin-induced mouse models showed that inhaled CL27c effectively reduced lung fibrosis by decreasing collagen deposition and downregulated key pro-fibrotic markers, including TGF-β1, CTGF, Collagen type I (Col1a1), and matrix metalloproteinase-2 (MMP2)." (PMID 40248697, 2025). "When stimulated by inflammation, macrophages secrete MMP2 and MMP9 to promote degradation of the surrounding matrix, thereby expanding the inflammatory response, which may be one of the reasons why the expression of MMPs is positively correlated with pulmonary fibrosis." (PMID 40181990, 2025).
lung adenocarcinoma (62 papers, 1999 to 2026). A carcinoma that arises from the lung and is characterized by the presence of malignant glandular epithelial cells. "The clinicopathological correlations with the expressions of both POU5F1 and MMP2 were examined on a TMA containing 55 lung adenocarcinoma specimens to elucidate their associations with the survival of LAC patients." (PMID 24386189, 2013). "PLK1 inhibition suppresses the migration of A549 lung adenocarcinoma cells by decreasing MMP2 and VEGFA expression." (PMID 38355643, 2024). "MMP-2 and MMP-9 were identified as factors associated with the metastatic phenotype of lung adenocarcinoma cells." (PMID 34204745, 2021). "Alpha-tomatine inactivates PI3K/Akt and ERK signaling pathways and nuclear factor (NF)-κB and AP-1 binding activities to inhibit the invasion and migration of human lung adenocarcinoma A549 cells by reducing u-PA MMP-2 and MMP-9." (PMID 31941156, 2020). "A previous study suggests that the expression of MMP2 in lung squamous cell carcinoma is higher than that in lung adenocarcinoma, and its high expression is closely related to lymph node metastasis and TNM staging, and affects the prognosis of patients." (PMID 33115469, 2020). "PPAR-related mechanisms have been used in experimental models to inhibit key genes involved in tumorigenesis, such as matrix metalloproteinase 2 (MMP-2) in the lung adenocarcinoma cell line A549." (PMID 31216637, 2019). "Stathmin silencing led to the mRNA downregulation of P38 and MMP2 in lung adenocarcinoma PC-9 cells (p<0.05)." (PMID 27494889, 2017). "We recently showed that CIP4 promotes activation of an EGFR/ERK/Zeb1/MMP-2 axis in lung adenocarcinoma cells and tumors, and it will be interesting to further test this axis in CIP4 KD breast tumors." (PMID 25823823, 2015). "The expression and activity of MMP-2 in response to CCL25 were greater in lung adenocarcinoma cells compared with squamous cell carcinoma cells." (PMID 26168791, 2015). "The clinical significance of POU5F1 and matrix metalloproteinase 2 (MMP-2) expressions in the patients with lung adenocarcinoma (LAC) was also investigated." (PMID 24386189, 2013). "Using the criteria described before, high expressions of POU5F1 and MMP-2 were observed in 26 (47.3%) and 39 (70.9%) of 55 lung adenocarcinoma specimens respectively." (PMID 24386189, 2013). "In lung adenocarcinoma cells MMP-2 siRNA induces Fas-mediated activation of caspase-8 and -9 and cleavage of Bid by increasing Fas and FasL in both in the cell membrane and in the medium." (PMID 23470450, 2013). "CL1-5 cells, a human lung adenocarcinoma cell line, expressed an elevated level of MMP-2, MMP-9 and exhibited a highly invasive and metastatic ability." (PMID 22454661, 2012). "The aim of this study is to investigate CD147 and MMP-2 expression in squamous cell carcinoma and adenocarcinoma of the lungs and to analyze their clinical significance." (PMID 21924036, 2011). "Gelatin zymographs of conditioned media derived from human lung adenocarcinoma cell lines revealed two major bands of gelatinase activity at 68 and 92 kDa, which were characterized as matrix metalloproteinase (MMP)-2 and MMP-9 respectively." (PMID 10408691, 1999). "This led us to further speculate that GPX2 may enhance the invasive ability of lung adenocarcinoma A549 cells by controlling the expression of MMP2 and MMP9 proteins in lung adenocarcinoma cells." (PMID 35898928, 2022). "In addition, RGCC can induce EMT and enhance the migration and invasion of lung adenocarcinoma cells through increased MMP2 and MMP9 production and activity." (PMID 34015051, 2021). "We found that AFG1-induced lung adenocarcinoma expressed high levels of MMP-2 and MMP-9." (PMID 28801561, 2017).
lung adenocarcinoma (continued). "Previously, Nadroparin has been suggested to reduce the invasive, migratory, and adhesive ability of human lung adenocarcinoma A549 cells by down-regulating the expression of integrin β1 and β3 as well as matrix MMP2 and 9 and by restraining the actin cytoskeleton reorganization." (PMID 29023465, 2017). "Here, we demonstrated that Crk induced EMT in A549 human lung adenocarcinoma cells through differential regulation of Rac1/Snail and RhoA/Slug, leading to decreased expression of E-cadherin and increased N-cadherin, fibronectin, and MMP2 expression." (PMID 27027347, 2016). "The expression of POU5F1 and MMP-2 in 55 cases of lung adenocarcinoma." (PMID 24386189, 2013). "Moreover, the CD147 and MMP-2 expression in squamous cell carcinoma and adenocarcinoma of the lungs were related to lymph node metastasis and TNM stages (P < 0.05), but not to age, gender and histologic type (P > 0.05)." (PMID 21924036, 2011). "CD147 and MMP-2 expression is correlated with the invasion and metastasis of squamous cell carcinoma and adenocarcinoma of the lungs and may be used as objective markers for predicting the behavior of squamous cell carcinoma and adenocarcinoma of the lungs." (PMID 21924036, 2011). "Consequently, the reduction of MMP-2/-9 by TF-siRNA exactly results in attenuating the metastatic potency of lung adenocarcinoma cells." (PMID 21619686, 2011). "It is well documented that MMPs, in particular MMP-2 and MMP-9, which digest type-IV collagen and ECM, are strongly associated with the metastatic potential of many types of tumour cells, and their over-expression confers a worse prognosis in the early stage of lung adenocarcinoma." (PMID 34204745, 2021). "In lung adenocarcinoma (LUAD), RGCC stimulates epithelial-mesenchymal transition (EMT), enhances cell migration and invasion, and reduces MMP-2 and MMP-9 protein activity and expression." (PMID 37576389, 2023). "In the same line, TGF-β-treated human lung adenocarcinoma cells secrete EVs that are enriched in lnc-MMP2-2, which promotes the expression of MMP-2, regulating migration and invasion of lung cancer cells and intravasation into the vasculature." (PMID 35493080, 2022). "Subsequently, it is verified that 9 core targets for ginseng treatment of lung adenocarcinoma, namely, JUN, IL-1β, IL-2, ICAM1, HMOX1, MMP9, MMP2, PTGS2, and TNF, are closely related to the proliferation, migration, and apoptosis of lung adenocarcinoma cells." (PMID 32802118, 2020). "The downregulation of p38 MAPK and JNK was shown to result in decreased MMP-2 and MMP-9 expressions in human lung adenocarcinoma cells." (PMID 33381308, 2020). "A previous study shows that Gabra3 induced MMP-2 and MMP-9 expression through activating the JNK signaling pathway, which enhanced lymphatic metastasis in lung adenocarcinoma." (PMID 29078789, 2017). "Western blot results showed elevated expression of MMP-2 and MMP-9 in the lung tissues of mice with AFG1-induced lung adenocarcinoma." (PMID 28801561, 2017). "The expression of TNF-α, IL-6, and macrophage marker CD68, as well as E-cadherin, vimentin, Twist, matrix metalloproteinase (MMP)-2, MMP-9, and SOD-2 were examined in AFG1-induced lung adenocarcinoma." (PMID 28801561, 2017). "Higher expressions of MMP2 and MMP9 have also been correlated with poor prognosis in early stages of lung adenocarcinoma." (PMID 24811863, 2014). "Our study also found a higher expression of MMP-2 in LPA, suggesting the role of MMP-2 in the development of lung adenocarcinoma." (PMID 23591077, 2013). "Here, we demonstrated that CSLCs-derived from lung adenocarcinoma (LAC) cells displayed highly invasive and migratory capabilities via expressing high levels of POU5F1 and MMP-2." (PMID 24386189, 2013).
lung adenocarcinoma (continued). "In particular, induction of miR-486-5p suppressed MMP-2 and MMP-9 protein expression in human colorectal cancer cell lines as well as in human lung adenocarcinoma cell lines, suggesting that an epigenetic mechanism by which doxycycline affects MMP expression occurs via the induction of miR-486." (PMID 33920915, 2021). "Forced LINC00461 expression decreased expression of miR‐195 and Bax, increased expression of HOXA10, MMP‐2, MMP‐9 and Bcl‐2, promoted cell proliferation, migration and invasion as well as tumour formation, and enhanced radiosensitivity of lung adenocarcinoma cells." (PMID 31967713, 2020). "Meanwhile, according to the results of qRT-PCR, it is speculated that ginseng can treat lung adenocarcinoma by up-regulated JUN, IL-1β, IL-2, ICAM1, HMOX1, MMP9, and MMP2 targets and down-regulated PTGS2 and TNF genes." (PMID 32802118, 2020). "A previous study demonstrated that EGCG could repress the activities of MMP-2 and MMP-9 in highly invasive CL1-5 lung adenocarcinoma cells." (PMID 32198390, 2020). "Moreover, tomatidine inhibits the invasion of human lung adenocarcinoma A549 cells through the suppression of ERK and Akt pathways and MMP-2 and 9 expressions." (PMID 31941156, 2020). "In addition, GABRA3 induced MMP-2 and MMP-9 expression through activation of the JNK/AP-1 signaling pathway, which enhanced lymphatic metastasis by lung adenocarcinoma both in vitro and in vivo." (PMID 27081042, 2016). "Four genes (MMP-2, c-fos, claudin 1 (CLDN1) and claudin 10(CLDN10)) were correlated with the results of microarray and real time RT-PCR analyses for the gene-expression data in samples from 41 patients with lung adenocarcinoma." (PMID 23591077, 2013). "The present study suggests that HPV infection may be involved in angiogenic promotion mediated by IL-8, MMP-2, MMP-9 up-regulation in lung adenocarcinoma." (PMID 23349885, 2013). "When AKR1B10 is silenced in lung adenocarcinoma cells, it suppresses their extravasation through the BBB in vitro, ex vivo microfluidic chip, and in vivo models; moreover, AKR1B10 silencing induced the downregulation of metastatic cells’ expression of matrix metalloproteinase MMP-2 and MMP-9." (PMID 39408656, 2024). "Thus, ablation of the GRK6-mediated repression of MMP-2 and MMP-7 may increase the invasiveness of lung adenocarcinoma cells." (PMID 33920915, 2021). "Of all human MMPs described so far, gelatinases (or type IV collagenases), i.e., MMP-2 (gelatinase-A) and MMP-9 (gelatinase-B), are recognized to be apparently correlated with pathological grading, staging, metastasis, and poor prognosis in patients with lung adenocarcinoma." (PMID 34204745, 2021). "Furthermore, miR-145 inhibited cell proliferation and promoted cell apoptosis through negatively regulating mTOR signaling pathway and decreasing MMP-2 and MMP-9 expression, the Bax/Bcl-2 ratio and the activity of the caspase-3 cascade in human lung adenocarcinoma A549 cells." (PMID 31582906, 2019). "Not surprisingly, our study indicated that MMP-2 may play an important role in the progression of lung adenocarcinoma." (PMID 23591077, 2013). "However, studies have also found that ESR2 may be a new therapeutic target for lung adenocarcinoma in the future, as its downregulation reduces matrix metallopeptidase 2 (MMP-2) and MMP-9 expression, inhibiting the progression of lung adenocarcinoma through the MEK/ERK signaling pathway." (PMID 33868436, 2021).
fibrosarcoma (59 papers, 2002 to 2025). A malignant mesenchymal fibroblastic neoplasm affecting the soft tissue and bone. "Extracellular forms of Hsp90 linked to the activation of MMP-2 on fibrosarcoma cells act by interacting with Hsp70, Hsp40, Hop, p23, and Hip in an ATP-independent manner." (PMID 39936995, 2025). "Such downregulation of MMP2 is associated with decreased metastatic potential, suggesting that miR-29 could serve as a therapeutic target to reduce the invasiveness of fibrosarcoma cells." (PMID 39594601, 2024). "The overexpression of miR-29 family members in fibrosarcoma cell lines reduced MMP2 expression, impairing cell invasion and migration." (PMID 39594601, 2024). "The miR-29 family (miR-29a, miR-29b, miR-29c) plays a tumor-suppressive role in fibrosarcoma by targeting MMP2, a matrix metalloproteinase involved in extracellular matrix remodeling and tumor invasion." (PMID 39594601, 2024). "Jay’s group at Tufts University first reported that a secreted protein from the conditioned medium of a fibrosarcoma cell line, HT-1080, promoted tumor cell invasion in vitro by activating the matrix metalloproteinase 2 (MMP2)." (PMID 36672211, 2023). "The expression of MMP–2 on the surface of cancer cells was described in studies conducted on fibrosarcoma and colorectal and breast cancerwhere the authors have revealed that platelet and MMP–2 manifested by cancer cells contribute to TCIPA." (PMID 35814405, 2022). "The HT1080 cell line is derived from a human fibrosarcoma to mimic stromal fibroblasts and is sustained to express MMP-2 and MMP-9." (PMID 33926142, 2021). "Given that an MMP-cleaved CPP-Dox can inhibit proliferation in Dox-resistant cancer cell lines, this ELP-mmpL-CPP-Dox system was further validated using HT-1080, a fibrosarcoma cancer cell producing endogenous MMP-2 and MMP-9." (PMID 33498762, 2021). "Cancer cell MMP-2 membrane expression was observed in different cancer types, such as fibrosarcoma, colorectal and breast carcinomas." (PMID 30441823, 2018). "The study showed that PB inhibited cell proliferation of human fibrosarcoma cells by 60% at 25 μg/mL and 80% at 50 μg/mL, and inhibited both MMP-2 and -9 secretion in a dose-dependent manner, with total inhibition at 50 μg/mL." (PMID 27618095, 2016). "Fibrosarcoma, chondrosarcoma, liposarcoma and synovial sarcoma showed bands corresponding to MMP-2 and MMP-9 with dose-dependent enhancement of MMP-9 with phorbol 12-myristate 13-acetate (PMA) treatment." (PMID 24085323, 2013). "Actinomycin-D, cyclohexamide, retinoic acid, and dexamethasone inhibited MMP-2 and -9 in chondrosarcoma and fibrosarcoma cells." (PMID 24085323, 2013). "Liposarcoma showed block of MMP-2 at 500 μg/ml and MMP-9 at 1000 μg/ml, while fibrosarcoma and chondrosarcoma showed block of MMP-2 at 1000 μg/ml and virtual block of MMP-9 at 1000 μg/ml." (PMID 24085323, 2013). "MMP-2 expression was downregulated by 99% by doxycycline 100 μM in chondrosarcoma by 100% in fibrosarcoma and by 99% in liposarcoma." (PMID 24085323, 2013). "On gelatinase zymography, fibrosarcoma, chondrosarcoma, liposarcoma and synovial sarcoma showed bands corresponding to MMP-2 and MMP-9 with enhancement of MMP-9 with PMA (100 ng/ml) treatment." (PMID 23661254, 2013). "In this study, we focused on the modulating effect of NM on the activities of MMP-2 and -9, TIMPs and u-PA in adult human sarcomas: fibrosarcoma, chondrosarcoma, liposarcoma, synovial sarcoma and uterine leimyosarcoma cell lines." (PMID 23661254, 2013). "We found that fibrosarcoma HT-1080, chondrosarcoma SW-1353, liposarcoma SW-872 and synovial sarcoma SW-982 normally expressed both MMP-2 and MMP-9." (PMID 24085323, 2013). "IL-1β stimulated MMP-9 and MMP-2 in chondrosarcoma cells, enhanced levels of both MMPs at 1 ng/ml but decreased levels at 25 ng/ml in fibrosarcoma, inhibited MMP-2 and enhanced MMP-9 at 1 and 10 ng/ml and downregulated at 25 ng/ml in liposarcoma cells." (PMID 24085323, 2013).